SNHG9 (small nucleolar RNA host gene 9)
Diseases named in the same sentence as SNHG9 in open-access papers (continued):
Sharing a sentence is not in itself a finding about the gene and the disease.
tumor (12 papers, 2020 to 2025). "Beyond upstream regulatory factors, a lipid-associated lncRNA, small nucleolar RNA host gene 9 (SNHG9), has been identified as an oncogenic lncRNA that promotes tumor progression." (PMID 41280670, 2025). "Considering that among the ClncRNAs, SNHG9 exhibited the most significantly differential expression between tumor and normal samples, it was selected for further cellular experimental validation." (PMID 39530098, 2024). "Further, we compared the relative expression of SNHG9, and miR-23a-5p and found a significant low expression of SNHG9 expression in sh-SNHG9 group mice tumor tissue than in sh-NC group mice tumor tissue." (PMID 34539877, 2021). "The xenograft tumorgenicity test showed SNHG9 downregulation significantly inhibited the tumor growth in BALB/c mice." (PMID 34539877, 2021). "A high SNHG9 expression in tumor tissues was a predictive of shorter overall survival time (p < 0.01)." (PMID 32294932, 2020). "SNHG9, affiliated with the lncRNA class, is an RNA gene that is currently believed to promote the proliferation of various types of tumor cells through multiple pathways, including phosphatidylinositol binding, inhibition of autophagy, and participation in methylation regulation." (PMID 37822943, 2023). "Additionally, a tumor-promoting long non-coding RNA (lncRNA) known as small nucleolar RNA host gene 9 (SNHG9) has been found to identified to drive the liquid droplet formation of Large Tumor Suppressor Kinase 1 (LATS1) and inhibits the Hippo pathway." (PMID 37580790, 2023). "Similarly, MIR4435-2HG and SNHG9 expressions were found to be significantly higher in patients with larger tumor size (≥5 cm) in comparison with smaller tumor size (<5 cm) (p = 0.005 and p < 0.001, respectively)." (PMID 35887228, 2022). "Therefore, SNHG9 is overexpressed in human PTC tissues and is related to tumor malignancy, suggesting that SNHG9 plays an oncogenic role in PTC." (PMID 34017682, 2021). "High SNHG9 expression was significantly associated with a large tumor size (P=0.034) but did not correlate with tumor invasion, lymph node metastasis or other variables." (PMID 34017682, 2021).
infection (2 papers, 2016 to 2022). The state of being infected such as from the introduction of a foreign agent such as serum, vaccine, antigenic substance or organism. "It was inferred that SNHG9 regulates viral replication through the miR-150-5p/c-Fos axis to affect EV-D68 infection of RD cells." (PMID 36741904, 2022). "By regulating the miR-150-5p/c-Fos axis, our study demonstrated that SNHG9 overexpression inhibits viral multiplication in EV-D68 infection." (PMID 36741904, 2022). "SNHG9, a long intergenic noncoding RNA, has 2 isoforms, 00087626 and 00087627, the infection resulted in the significant expression of isoform 00087627 (note the boxed area)." (PMID 27354008, 2016).
SNHG9 also shares sentences with these, for which no sentence is quoted: prostate carcinoma (3 papers); hepatocellular carcinoma (2); Abdominal obesity (1); bladder cancer (1); cervical cancer (1); non-small cell lung carcinoma (1); pancreatic (1); triple-negative breast carcinoma (1).